NGRN (neugrin, neurite outgrowth associated)
Description:
Plays an essential role in mitochondrial ribosome biogenesis. As a component of a functional protein-RNA module, consisting of RCC1L, NGRN, RPUSD3, RPUSD4, TRUB2, FASTKD2 and 16S mitochondrial ribosomal RNA (16S mt-rRNA), controls 16S mt-rRNA abundance and is required for intra-mitochondrial translation of core subunits of the oxidative phosphorylation system.
Synonyms: DSC92
Tractability: Antibody: UniProt places it where antibodies can reach, with high confidence; UniProt predicts a signal peptide or a membrane-spanning region; its Gene Ontology location is reachable by antibodies, with medium confidence. PROTAC: ubiquitination databases record sites on it; its protein half-life has been measured.
Gene: Protein-coding gene on chromosome 15 (90,265,659 to 90,275,778, forward strand). Ensembl gene ENSG00000182768.
Subcellular location: Nucleus; Secreted; Mitochondrion membrane
Subcellular location (Human Protein Atlas): Mitochondria; Cytokinetic bridge; Nucleoplasm
Pathways (Reactome):
Metabolism of RNA: Mitochondrial mRNA modification; rRNA modification in the mitochondrion
Gene Ontology:
Molecular function: protein binding; RNA binding; rRNA binding
Biological process: mitochondrial ribosome assembly; positive regulation of mitochondrial translation; neuron differentiation
Cellular component: mitochondrial matrix; mitochondrial membrane; mitochondrion; nucleoplasm; nucleus; extracellular region
Genetic constraint (gnomAD): Loss-of-function variants: 13 observed, 12.65 expected, observed/expected ratio (o/e) 1.03, 90% interval 0.67 to 1.62. The upper end of that interval is the gene's LOEUF score, 1.62, which puts it in group 6 of 6, group 1 being the genes least tolerant of losing a copy. Missense variants: 397 observed, 376.12 expected, observed/expected ratio (o/e) 1.06, 90% interval 0.97 to 1.15. Synonymous variants: 149 observed, 154.35 expected, observed/expected ratio (o/e) 0.97, 90% interval 0.84 to 1.11.
Homologues: Orthologues: chimpanzee NGRN (98% identical), macaque NGRN (93% identical), dog NGRN (79% identical), pig NGRN (75% identical), rat Ngrn (73% identical), mouse Ngrn (72% identical), rabbit NGRN (71% identical), guinea pig NGRN (68% identical), tropical clawed frog ngrn (36% identical), zebrafish ngrn (31% identical).
Diseases named in the same sentence as NGRN in open-access papers:
NGRN is named in the same sentence as 6 diseases in open-access papers, as found by Europe PMC text mining. Sharing a sentence is not in itself a finding about the gene and the disease. The quoted sentences say what the papers report.
colorectal cancer (1 paper, 2026). A primary or metastatic malignant neoplasm that affects the colon or rectum. "Collectively, our findings identify PCBP3 and NGRN as promising prognostic biomarkers and potential therapeutic targets in colorectal cancer and provide new insights into the role of RNA metabolism in colorectal cancer progression and tumour immune regulation." (PMID 42271539, 2026). "Functional experiments demonstrated that silencing PCBP3 or NGRN significantly inhibited the proliferation and invasion of HCT116 colorectal cancer cells." (PMID 42271539, 2026).
cardiovascular diseases (1 paper, 2022). "In the dilated stage, TMEM205, ADIRF, C6H4orf48, NGRN, PROSER1, ERICH2, and CINP were not previously linked to cardiovascular diseases." (PMID 35625658, 2022).
NGRN also shares sentences with these, for which no sentence is quoted: amyotrophic lateral sclerosis (1 paper); cancer (1); pancreatic cancer (1); tumour (1).